IL17A (interleukin 17A)
Diseases named in the same sentence as IL17A in open-access papers (continued):
Sharing a sentence is not in itself a finding about the gene and the disease.
systemic sclerosis (59 papers, 2012 to 2026). A chronic disorder, possibly autoimmune, marked by excessive production of collagen which results in hardening and thickening of body tissues. "In systemic sclerosis lesions, quantitative analysis demonstrated elevated IL-17A concentrations relative to those in healthy controls." (PMID 40536951, 2026). "Elevated IL-17A concentrations promote vascular fibrosis in systemic sclerosis patients by triggering the ERK1/2 pathway in vascular smooth muscle cells within the dermis." (PMID 40536951, 2026). "The possible role of IL-17 in ILD is highlighted in systemic sclerosis patients by significantly elevated IL-17A levels in the patients with ILD compared to controls." (PMID 40869458, 2025). "Elevated levels of IL-17A have also been reported in patients with IPF and systemic sclerosis-associated ILD, suggesting its involvement in chronic inflammatory circuits that contribute to fibrotic progression." (PMID 40612945, 2025). "For example, it was reported that the level of serum IL‐17A in patients with systemic sclerosis was 1.36 ± 8.27 pg/mL and in healthy control group was 0.59 ± 1.96 pg/mL." (PMID 39946217, 2025). "IL-17A has been reported to promote the fibrosis of systemic sclerosis by increasing inflammation and the proliferation and collagen deposition of fibroblasts." (PMID 39872534, 2024). "This approach has been previously used in a study which investigated systemic sclerosis, where CG and lower severity diseases group had levels of IL-17A below the LOD and thus have used 0 pg/mL as the median in order to perform statistical analysis." (PMID 37569857, 2023). "Conversely, IL-17A acts synergistically with TGF-β to increase the expression of IL-6 in fibroblasts cultured from systemic sclerosis patients." (PMID 32365896, 2020). "In this respect, in human systemic sclerosis skin fibroblasts, IL-17A reduced TGF-β1-induced collagen production and α-SMA expression and downregulated CTGF expression." (PMID 32987705, 2020). "Nevertheless, specific cytokines which were detected in such low levels in AAV were significantly elevated in systemic sclerosis: IL-4, IL-6, IL-17A, and IL-22." (PMID 31286195, 2019). "IL-17A-producing T cells are characteristically increased in peripheral blood of patients with systemic sclerosis (SSc) and they are characterized by expression of chemokine receptor CCR6 responsible for with skin- and lung-homing capabilities." (PMID 26062902, 2015). "High interleukin (IL)-17A levels are characteristically found in the skin of systemic sclerosis (SSc) individuals." (PMID 25136988, 2014). "In systemic scleroderma, such IFN gamma/IL-17A double-positive cells could be linked directly to fibrosis regulation through IL-21 release, and in PSC, expansion of IFN gamma coexpressing TH17 cells was observed after in vitro stimulation with bacterial antigens." (PMID 37256725, 2023). "Furthermore, there is increasing evidence to suggest that IL-17A may also have a central role in the pathogenesis of systemic sclerosis, a progressive fibrotic disorder." (PMID 34544860, 2021). "Recent reports have demonstrated that endothelial cells are involved in vascular inflammatory injury in systemic sclerosis (SSc) and interleukin-17A (IL-17A) plays a crucial role in the pathogenesis of SSC." (PMID 24376862, 2013). "It has been discovered that IL-17A secreted by Th17 cells augments the release of pro-inflammatory chemokines, including monocyte chemoattractant protein (MCP)-1 and IL-8, from dermal fibroblasts in systemic sclerosis." (PMID 39872534, 2024). "Besides, significantly higher frequency of circulating, skin, and lung infiltrating Th17 cells and higher levels of serum, skin, and lung IL-17A, TGF-β1, IL-6, and RORγt were detected in mice in a bleomycin-induced murine model of systemic sclerosis." (PMID 33672430, 2021).
systemic sclerosis (continued). "Thus, in cultured dermal vascular smooth muscle cells and fibroblasts from systemic sclerosis patients, IL-17A stimulated proinflammatory responses, ECM protein secretion, proliferation, and migration, supporting the profibrotic role of IL-17A." (PMID 32987705, 2020). "In systemic sclerosis (SSc), IL-22 synergistically works with TNFα to induce the expression of IL-8 and CCL2 in skin fibroblasts, while the simultaneous stimulation of TGF-β1 and IL-17A can lead to an up-regulation of IL-6 expression in fibroblasts from affected skin by nearly a hundredfold." (PMID 35967331, 2022).
acute respiratory distress syndrome (58 papers, 2011 to 2026). Progressive and life-threatening pulmonary distress in the absence of an underlying pulmonary condition, usually following major trauma or surgery. "Although IL-17A has been shown to play both protective and pathogenic roles in chronic P. aeruginosa infections, its role in acute P. aeruginosa infections, such as acute respiratory distress syndrome and VAP, seems to be unclear." (PMID 36033859, 2022). "This suggestion is consistent with reports that IL-17A increases early in experimental pneumococcal pneumonia, and is an early marker of likely disease severity and development of acute respiratory distress syndrome in Covid-19 patients." (PMID 41379768, 2025). "Additional murine studies using FMT have demonstrated increased murine survival after acute liver injury and during acute respiratory distress syndrome by decreasing IL-17A levels." (PMID 36543914, 2022). "Serum IL17A levels were elevated in bacterial sepsis patients with acute respiratory distress syndrome (ARDS) and in animal models of abdominal bacterial infection." (PMID 22026963, 2011). "However, IL-17A-mediated recruitment of inflammatory cells such as neutrophils likely contributes to lung damage in severe pneumonia and acute respiratory distress syndrome (ARDS)." (PMID 35883573, 2022). "The binding of SARS-CoV-2’s spike protein to ACE2 leads to dysregulation, contributing to acute respiratory distress syndrome (ARDS), hypertension, and the overproduction of cytokines such as IL-1β, IL-17A, and IL-18." (PMID 40003732, 2025). "For example, in mice with lipopolysaccharide-induced acute respiratory distress syndrome (ARDS), levels of IL-17A were elevated in plasma, lung tissue lysate, and bronchoalveolar lavage fluid." (PMID 35422004, 2022).
emphysema (57 papers, 2011 to 2026). "In our study, we found that epithelial/stromal cells secrete G-CSF in response to IL-17A produced by γδ+ T cells in an emphysema model, driving the differentiation of pathogenic Siglec-F+ neutrophils." (PMID 40461699, 2025). "IL-17A plays a significant role in the development of PPE-induced emphysema, and its deficiency has been shown to delay disease progression." (PMID 40461699, 2025). "To explore this association, we induced emphysema in IL-17A-knockout (IL-17AKO) mice and examined changes in the population of Siglec-F+ neutrophils." (PMID 40461699, 2025). "Intriguingly, interleukin (IL)-17A is known to stimulate bicarbonate secretion in bronchial epithelial cells, and CS-induced emphysema is milder in IL-17A-deficient than normal mice." (PMID 34822707, 2021). "Both neutrophil recruitment to the lung and airspace enlargement in murine model of elastase-induced emphysema were again only partially attenuated in Il17a deficient mice." (PMID 34075087, 2021). "Here, we investigated the role of IL-17 in the development of elastase-inducible emphysema using IL-17A-deficient (IL-17A−/−) mice." (PMID 23331548, 2013). "Separately, emphysema was attenuated in IL-17A- and IL-17RA-deficient mice exposed to long-term cigarette smoke, compared to wild-type controls, and IL-1RI–dependent IL-17A was found to be critical for pulmonary neutrophilia in H. influenzae-induced acute exacerbation using the same model." (PMID 35275333, 2023). "Furthermore, Il17a and Il17f dual deficient mice were protected against enlargement of airspaces (emphysema) due to long-term cigarette exposure." (PMID 34075087, 2021). "IL-17A deficient mice show reduced pathology in models of smoking induced emphysema." (PMID 30761142, 2019). "In a model of elastase-induced pulmonary emphysema we examined the response of IL-17A-deficient mice, monitoring airway inflammation, static compliance, lung histology and levels of neutrophil-related chemokine and pro-inflammatory cytokines in bronchoalveolar lavage (BAL) fluid." (PMID 23331548, 2013). "In tissue remodeling, IL-17A induces alveolar epithelial ferroptosis via the ACT1-TRAF6-p38 MAPK cascade to drive emphysema." (PMID 42292489, 2026). "Neutralizing IL-17A also reduced the number of Siglec-F+ neutrophils in emphysema-induced mice, mirroring the effect observed in IL-17A-deficient mice." (PMID 40461699, 2025). "To further investigate the correlation between IL-17A and Siglec-F+ neutrophils during emphysema progression, we examined the kinetics of Siglec-F+ neutrophil frequency and the IL-17A concentration." (PMID 40461699, 2025). "Although IL-17A was also expressed by ILC3s in emphysema, the frequency and absolute cell number of IL-17A+ ILC3s were markedly lower than those of γδ+ T cells." (PMID 40461699, 2025). "In COPD patients, T cells in the peripheral airways exhibit an enhanced ability to express CXCR3 and IFN-γ, and increased IL-17A secretion from Th17 cells, along with its signature protein RORγt, is directly correlated with the severity of emphysema." (PMID 40034710, 2025). "Transient increases of IL-17A shortly after N. brasiliensis infection activates emphysema that impairs alveolar structures." (PMID 36691020, 2023). "This suggests that both IL-17A and F play an interactive role in the development of emphysema, so that these cytokines or their common receptors need a total block to provide the maximum benefit in COPD and severe neutrophilic asthma." (PMID 34075087, 2021). "IL-17A is implicated in COPD-associated pathogenic responses, including emphysema, lymphoid neogenesis, corticosteroid resistance, dysbiosis, mucus hypersecretion, and ongoing inflammation despite smoking cessation." (PMID 30383540, 2019). "To elucidate the role of IL-17A in the development of emphysema, we examined lung function 21 days following PPE treatment." (PMID 23331548, 2013).
emphysema (continued). "To further characterize the development of emphysema in IL-17A−/− mice, we determined the airspace enlargement by measuring the mean linear intercept (Lm) in 20 randomly selected fields from H&E stained tissue sections." (PMID 23331548, 2013). "In the present study, to elucidate the role of IL-17A in the development of emphysema, we investigated PPE-induced initial inflammation and subsequent late phase emphysematous change in IL-17A−/− and WT mice." (PMID 23331548, 2013). "Following PPE installation, IL-17A levels increased rapidly within a day and then gradually declined, whereas the frequency of Siglec-F+ neutrophils increased from day 2 to day 4 after emphysema onset and subsequently declined." (PMID 40461699, 2025). "Furthermore, ablation of the Mirlet7b/Mirlet7c2 cluster enhanced CD8+IL17a+ T cells (Tc17) formation in emphysema development in mice." (PMID 38722677, 2024). "Furthermore, ablation of the let-7b/let-7c2-cluster enhanced CD8+IL17a+ T cells (Tc17) formation in emphysema development in mice." (PMID 37905101, 2024). "However, lung B cells can produce RELMα to downregulate IL-17A of γδ T cells, thereby limiting emphysema." (PMID 36691020, 2023). "Furthermore, genetic ablation of the IL-17R in experimental CS models protected the mice against the development of emphysema, hence identifying IL-17A as a major inflammatory cytokine that can drive pathological inflammation." (PMID 25405776, 2014). "Our data suggest that targeting IL-17A in emphysema may be a hopeful therapeutic strategy for improving clinical outcomes and for delaying disease progression." (PMID 23331548, 2013). "Although IL-17A contributes to many chronic inflammatory diseases, it’s role in the inflammatory response of elastase-induced emphysema remains unclear." (PMID 23331548, 2013). "Targeting IL-17A in emphysema may be a potential therapeutic strategy for delaying disease progression." (PMID 23331548, 2013). "In the present study, we demonstrated the importance of IL-17A for emphysema using IL-17A−/− mice." (PMID 23331548, 2013). "Our findings underscore the crucial role of Siglec-F+ neutrophils in the pathogenesis of PPE-induced emphysema and suggest that targeting the IL-17A/G-CSF axis or G-CSF receptor downstream signaling pathways may represent a promising therapeutic strategy for treating emphysema." (PMID 40461699, 2025). "In our study, one explanation for the mitigation of the emphysema was decreased levels of pro-inflammatory factors in the lungs (IL-1β and CXCL1/KC) and circulation (TNF-α, IL-1β, and IL-17A) by hUC-MSCs which may associate with the reduction of the neutrophil infiltration in emphysematous mice." (PMID 34646841, 2021). "Increased IL-17A levels in severe COPD patients are positively correlated with decreased lung functions and increased severity symptoms and emphysema, supporting an urgency to develop novel therapies modulating IL-17 or RORγ for COPD treatment." (PMID 35610240, 2022). "Mice with emphysema had an increased expression of Th1-type cytokine IFN-γ and Th17-type IL-17A and/or augmented numbers of Th17/Tc17 and Tc1 cells." (PMID 27902485, 2017). "Recently, it has also been reported that overexpression of IL-18 induced emphysema via IFN-γ and IL-17A, and induced mucus metaplasia via IL-13." (PMID 23331548, 2013). "IL-17A can also induce the release of matrix metalloproteinase (MMP)-9, which is involved in emphysema." (PMID 22032685, 2011). "Overall, our findings indicate that lung EpCAM+ epithelial cells and CD31+ blood endothelial cells are the major sources of G-CSF in lung epithelial/stromal cells when stimulated with IL-17A, which plays a pivotal role in the development of Siglec-F+ neutrophils in PPE-induced emphysema mice." (PMID 40461699, 2025).
emphysema (continued). "T-helper cells are characterized by the production of IL-17A, IL-17F, and IL-22, which can be released by eosinophils, neutrophils, CD8+ T cells, basophils, and mast cells, also playing a decisive role in experimental models of emphysema treated with elastase." (PMID 37834157, 2023). "Th17 cells, rather than IL-17A-secreting lung γδT cells, act as mediators of smoke-induced lung inflammation and emphysema." (PMID 34305606, 2021). "This indicated that IL-17A was not involved in the induction of emphysema but contributed to increase the effect of corticosteroids on attenuating the emphysema." (PMID 28194607, 2017). "Immunoreactive IL-17A+ cells increase in frequency in the submucosa of COPD patients and IL-17A expression is elevated in CS exposure models, where mice lacking IL-17RA were protected from developing emphysema." (PMID 25405776, 2014). "However, the relationship between IL-17A and Siglec-F+ neutrophils in emphysema is not well understood." (PMID 40461699, 2025). "Currently, it is generally believed that emphysema and severe airway obstruction are common clinical characteristics of COPD, and their evolvement and lymphoid neogenesis could be promoted by the up-regulation of IL-17A in COPD." (PMID 34305606, 2021). "Freshly isolated CD4+T cells from PBMC of ever-smokers without (controls; n = 61) or with emphysema (n = 95) that were stimulated with lung EFs showed specific induction of IL-6, IL-17A, and IFN-γ in emphysema (right three scatter plots) as compared to controls." (PMID 22969766, 2012). "In the present study, elastase-induced emphysematous changes of the lung in IL-17A−/− mice were reduced, but not completely attenuated compared to WT mice, suggesting that IL-17A may be essential but not sufficient for the full development of elastase-induced emphysema." (PMID 23331548, 2013).
amoebiasis (56 papers, 2015 to 2025). "Colonization with segmented filamentous bacteria (SFB) protected mice from amebiasis with an induced level of colonic IL-17A, IL-23, neutrophils, and dendritic cells and serum amyloid A (SAA)." (PMID 33502317, 2021). "Vaccinated mice lost protection to amebiasis when IFN-γ and IL-17A were neutralized." (PMID 33502317, 2021).